FAM241A (family with sequence similarity 241 member A)
Synonyms: C4orf32; FLJ39370
Tractability: Antibody: UniProt predicts a signal peptide or a membrane-spanning region. PROTAC: ubiquitination databases record sites on it.
Gene: Protein-coding gene on chromosome 4 (112,145,454 to 112,195,256, forward strand). Ensembl gene ENSG00000174749.
Subcellular location: Membrane
Subcellular location (Human Protein Atlas): Golgi apparatus
Gene Ontology:
Molecular function: protein binding
Cellular component: Golgi apparatus; membrane
Genetic constraint (gnomAD): Loss-of-function variants: 5 observed, 8.81 expected, observed/expected ratio (o/e) 0.57, 90% interval 0.3 to 1.19. That is too few expected variants to judge how well the gene tolerates losing a copy. Missense variants: 116 observed, 117.17 expected, observed/expected ratio (o/e) 0.99, 90% interval 0.85 to 1.15. Synonymous variants: 50 observed, 41.29 expected, observed/expected ratio (o/e) 1.21, 90% interval 0.96 to 1.53.
Homologues: Orthologues: chimpanzee FAM241A (98% identical), macaque FAM241A (94% identical), rabbit FAM241A (89% identical), dog FAM241A (89% identical), pig FAM241A (84% identical), mouse Fam241a (74% identical), rat Fam241a (65% identical), guinea pig FAM241A (57% identical), tropical clawed frog fam241a (43% identical), zebrafish fam241a (39% identical). Paralogues in human: FAM241B (22% identical).
Diseases named in the same sentence as FAM241A in open-access papers:
FAM241A is named in the same sentence as 8 diseases in open-access papers, as found by Europe PMC text mining. Sharing a sentence is not in itself a finding about the gene and the disease. The quoted sentences say what the papers report.
lung carcinoma (2 papers, 2022 to 2025). "ANXA2P1/miR-20b-5p/FAM241A (C4orf32) was discovered as a tumor suppressive regulatory axe in lung cancer." (PMID 39886652, 2025). "Next, three tumor suppressive ceRNA modules (ANXA2P1/miR-20b-5p/FAM241A, MIR99AHG/miR-218-5p/GPM6A, and SH3RF3-AS1/miR-34a-5p/HECW2) were analyzed to assess significance of their lung cancer survival rate prediction values." (PMID 36289596, 2022).
anal carcinoma (1 paper, 2019). "FAM241A is a potential target gene at this site, deleted through integration in our case of anal carcinoma." (PMID 30922253, 2019).
breast carcinoma (1 paper, 2025). "While there have been no reports on the study of FAM241A in GC, CXCR4 is the most widely expressed chemokine receptor in multiple cancers, including GC, breast cancer, and colorectal cancer." (PMID 39886652, 2025).
heart failure (1 paper, 2021). Inability of the heart to pump blood at an adequate rate to meet tissue metabolic requirements. "Three of the genes associated with heart failure had treatment cASE: FAM241A in five conditions (copper, dexamethasone, insulin, caffeine, and vitamin A); BAG3 in five conditions (dexamethasone, caffeine, vitamin A, nicotine, and aldosterone); and KLHL3 in triclosan." (PMID 33988505, 2021).
cancer (2 papers, 2022 to 2025). A tumor composed of atypical neoplastic, often pleomorphic cells that invade other tissues. "The ANXA2P1/miR-20b-5p/FAM241A axis provides a two-fold impact on tumor suppressor activities of cancer progression via ANXA2P1 and miR-20b-5p." (PMID 36289596, 2022).
tumor (2 papers, 2022 to 2025). "The bioinformatics analysis suggests that the tumor suppressor ANXA2P1/miR-20b-5p/FAM241A axis may have an impact on stemness signature via miR-20b-5p." (PMID 36289596, 2022). "Using the same rationale, we selected three regulatory axes for tumor suppression; these axes are designated as ANXA2P1/miR-20b-5p/FAM241A (C4orf32), MIR99AHG/miR-218-5p/GPM6A, and SH3RF3-AS1/miR-34a-5p/HECW2." (PMID 36289596, 2022). "In our study, we found that the HP infection score in the tumor group was notably higher than that in the normal group and screened five key prognostic genes (CTLA4, CPVL, EMB, CXCR4, and FAM241A) from the HP infection–related DEGs in STAD to establish a riskscore model." (PMID 39886652, 2025).
FAM241A also shares sentences with these, for which no sentence is quoted: colorectal cancer (1 paper); depression (1).